CD4 (CD4 molecule)
Diseases named in the same sentence as CD4 in open-access papers (continued):
Sharing a sentence is not in itself a finding about the gene and the disease.
narcolepsy (22 papers, 2014 to 2025). A sleep disorder characterized by a tendency for excessive sleepiness during the day which occurs even after adequate sleep in the nighttime. "These mice showed selective neuronal loss and developed narcolepsy-like symptoms only when both HA-specific CD4+ and CD8+ T cells were adoptively transferred." (PMID 35445831, 2022). "As the cause of the symptoms is the loss of hypocretin, we believe this population of autoreactive CD4+ T cells is very likely within the causal pathway for narcolepsy." (PMID 24825774, 2014). "Our current results indicate that narcolepsy, a disease caused by hypocretin cell loss, is associated with autoreactive CD4+ T cells recognizing fragments of hypocretin when presented by DQ0602, an HLA allele strongly associated with the disease." (PMID 24825774, 2014). "A sensitive T cell bank assay has revealed an increased prevalence of autoreactive CD4+ T cells in the bloodstream of individuals with narcolepsy." (PMID 39595997, 2024). "Our study contributes to the understanding of T cell–mediated reactivity in narcolepsy by extending previous findings related to both epitope-restricted reactivity of CD4+ T cells and phenotypic characterization of reactive cells." (PMID 35914171, 2022). "A better understanding of the narcolepsy disease mechanisms and of the potential role of cross-reactive CD4+ T cells has brought novel insights and refinements of the proposed hypothetical model." (PMID 36311717, 2022). "Altogether, these findings reveal RFX4-specific CD4+ T cells in both post-Pandemrix and early-onset narcolepsy patients, therefore suggesting involvement of RFX4 in T cell immunity of theses narcoleptic cases and controls." (PMID 33837283, 2021). "We identified several identical TCRβ sequences shared between unique narcolepsy CSF CD4+ T cell samples." (PMID 33482851, 2021). "infection, has also been implied by the presence of autoreactive orexin and other orexin-neuron antigen-specific CD4 and CD8 T cells, by the strong HLA association and by the presence of a skewed T cell receptor repertoire in narcolepsy patients." (PMID 34587172, 2021). "Overall, some autoreactive CD4+ T cells directed against RFX4 have been detected in narcolepsy patients, but also in healthy donors." (PMID 33837283, 2021). "While there appeared to be sporadic reactivity to some mutated motifs, we did not observe any significant differences in the frequencies of tetramer specific CD4 T cells in narcolepsy cases vs. controls." (PMID 33142956, 2020). "At this date, Dr. Elisabeth Mellins and I discovered that narcolepsy is characterized by the presence of autoreactive CD4+ T cells to hypocretin fragments when presented by DQ0602." (PMID 24825774, 2014). "A key experimental next step toward our understanding of narcolepsy is the identification of the culprit T-cell receptors (TCRs) cross-reactive with hypocretin on CD4+ T cells." (PMID 24825774, 2014). "These genetic studies suggest that CD4+ T-lymphocytes play a role in the pathogenesis of narcolepsy and support the biological plausibility of vaccinations as an environmental trigger of narcolepsy based on their immunomodulatory effects." (PMID 25501681, 2014). "Autoreactive CD4+ and CD8+ T cells recognizing hypocretin-related antigens have been demonstrated in patients, and adoptive transfer of antigen-specific T cells reproduces hypocretin-neuron loss and narcolepsy-like features in Orexin-HA mice." (PMID 41296378, 2025). "Furthermore, there was a significant increase in the frequency of circulating B cells and CD4+CXCR5+ follicular T cells among narcolepsy patients." (PMID 39595997, 2024). "Narcolepsy was hypothesized to be the result of molecular mimicry, with CD4+ T cells cross-reactive to hypocretin fragments leading to hypothalamic damage." (PMID 36352367, 2022).
narcolepsy (continued). "The role of AS03 may have been indispensable as a booster of the immune response triggering narcolepsy or as an inducer of strong cross-reactive and polyfunctional CD4 T-cell responses against viral antigens as earlier shown by the market authorization holder." (PMID 25501681, 2014). "This transcriptomics analysis aimed to characterize blood CD4 and CD8 T-cell subsets and determine their potential contributions to narcolepsy development." (PMID 38077397, 2023). "Of note, potential cross-reactive CD4+ T cell clones were found in HCRT- or HA-reactive T cell fractions isolated both from controls and NT patients independently on whether they were previously vaccinated with Pandemrix, thus challenging the model of a pathogenic role of these cells in narcolepsy." (PMID 35445831, 2022). "Overall, these observations point to a key role of autoreactive CD4+ and CD8+ cells in narcolepsy." (PMID 35445831, 2022). "While CD4+ T cells were able to infiltrate the brain and promote local inflammation but did not induce the disease, CD8+ T cells mediated neuronal damage and promoted the establishment of narcolepsy-like symptoms in this mouse model." (PMID 35445831, 2022). "The researchers then went on to evaluate the role of Pandemrix vaccination in this model, and their results confirm the data from the original work: induction of HA-specific CD4+ and CD8+ T cells in the HA-transgenic mouse model led to an “immunopathological process mimicking narcolepsy”." (PMID 36311717, 2022). "While hypothalamic inflammation was seen following injection of HA-specific CD4+ and/or CD8+ T cells, narcolepsy-like symptoms were only observed when activated CD8+ T cells were administered to the mice, pointing towards a role for CD8+ T-cell–mediated cytotoxicity." (PMID 36311717, 2022). "In this context, several lines of evidence converge on the notion that the presence of such cross-reactive CD4+ T cells alone is not a predictor for the narcolepsy pathogenesis." (PMID 36311717, 2022). "Single cell TCR sequencing and phenotyping of more RFX4 specific CD4+ and CD8+ T cells could elucidate the role of RFX4 in the pathophysiology of narcolepsy." (PMID 33837283, 2021). "Importantly, the enrichment of TRBV4-2 in one narcolepsy patient and one healthy donor suggests the involvement of RFX4 CD4+ T cell autoreactivity in these donors." (PMID 33837283, 2021). "A logical explanation for this observation could be that a TCR-mediated reactivity that involves receptors containing TRAJ24F, TRAJ28 and TRBV4-2 is an important step in the development of narcolepsy, perhaps through TCR recognition of a viral trigger or an autoantigen by CD4+ or CD8+ cells." (PMID 37188663, 2023). "Contrarily, bulk TCR sequencing analysis of CD4+ T cells reactive to HCRTNH2-tetramers or to pHA273–287-tetramers identified a few clones bearing shared TCR CDR3 sequences, thus further supporting a cross-reactive T cell immunity between self-antigens and viral antigens in narcolepsy." (PMID 35445831, 2022). "When presented to narcolepsy versus control CD4+ T cells, a differential activation in narcolepsy but not controls was found with HCRT56–68 and HCRT87–99, suggesting these may be involved in the pathophysiology of hypocretin cell loss in narcolepsy." (PMID 24825774, 2014). "Here, we present evidence of in vivo expansion of DQ6-HCRT tetramer+/TRAJ24+/CD4+ T cells in DQ6+ individuals with and without narcolepsy." (PMID 31748512, 2019).
Pneumocystis infection (22 papers, 2009 to 2024). "In CD4-deficient mice, the level of GM-CSF in lung tissues is increased after Pneumocystis infection." (PMID 37359523, 2023). "This has been demonstrated by the use of immunodeficient animal models, where loss of CD4+ T cells renders the animals susceptible to Pneumocystis infection." (PMID 31010170, 2019). "However, CD4-depleted FVB mice that were also depleted of AMs with clodronate-liposomes were rendered susceptible to Pneumocystis infection." (PMID 30283457, 2018). "In murine models, depletion of CD4+ T cells makes the mice susceptible to Pneumocystis infection." (PMID 29887863, 2018). "Because CD4+ T cells were the most expanded clonal cells after Pneumocystis infection, we performed sub-clustering analysis of CD4+ T cells from all five samples and identified six subclusters." (PMID 33959105, 2021). "For the CD4+ T cells, the D50 of the uninfected sample was 50.7, whereas the values for the Pneumocystis infection from weeks 1, 2, 3, and 4 were 51.3, 54.4, 52.2, and 56.5, respectively." (PMID 33959105, 2021). "Adaptive immune responses, especially CD4+T cells, play a central role in clearing Pneumocystis infection and directly influence clinical prognosis." (PMID 33959105, 2021). "Prior studies have shown that CD4+ T cell-mediated response is absolutely pivotal in controlling Pneumocystis infection, as we observed clonal expansion and decreased diversity of CD4+ T cells." (PMID 33959105, 2021). "Collectively, these results suggested that clonal CD4+ T cells expanded in lung tissues after Pneumocystis infection." (PMID 33959105, 2021). "SCID mice are able to salvage their ability to clear Pneumocystis infection effectively when reconstituted with CD4+ T cells from immunocompetent mice." (PMID 33669726, 2021). "Next, to determine if these TFs were not only affected in vitro in AMs following Pm stimulation but also in vivo during Pneumocystis infection, we further examined the transcription levels of both of the TFs in the CD4 lymphocyte-depleted mouse model of PCP." (PMID 34066663, 2021). "Quantification of cell subsets from scRNA-seq data demonstrated decreased fraction of naïve CD4 cells, while Th1, Th17, and Treg significantly increased after Pneumocystis infection." (PMID 33959105, 2021). "The key inflammatory cells which evoke inflammation in Pneumocystis infection include CD4+ T cells, alveolar macrophages, and neutrophils." (PMID 32149364, 2020). "The infection occurred with a higher CD4+ count (above 240) than the suspicious level of Pneumocystis infection in HIV patients, which was thought to be due to TNF-α use with HIV infection." (PMID 33209528, 2020). "In summary, these studies indicated a fundamental role for CD4+ T cell-mediated responses to Pneumocystis infection and also highlighted the participation of host airway cells in the immune response against Pneumocystis." (PMID 31010170, 2019). "CD4+ T cells are essential in controlling Pneumocystis infection, but the specific T helper cell subset that is indispensable is yet to be determined." (PMID 31010170, 2019). "In contrast, FVB mice treated with anti-CD4 plus anti-CD3 antibodies remained resistant to Pneumocystis infection." (PMID 30283457, 2018). "When CD4+ T cells depletion is stopped and CD4+ T cells are transferred into infected mice, the Pneumocystis infection is resolved." (PMID 29887863, 2018). "Although it has been well accepted that CD4+ T cells play a major role in controlling Pneumocystis infection, the potential mechanism is not well understood how the specific Th subsets mediate immunity responses to fight against PCP." (PMID 29887863, 2018). "The onset of PCP is typically related to CD4+ T cell count less than 200 cells/μL, which indicates the key role of this lymphocyte subset in defense against Pneumocystis infection." (PMID 29887863, 2018). "It has been well accepted that CD4+ T cells play a major role in controlling Pneumocystis infection." (PMID 29887863, 2018).
Pneumocystis infection (continued). "We found that loss of CD8+ T-cells or macrophages alone or in the context of CD4+ T-cell depletion significantly impaired the ability of the host to clear Pneumocystis infection." (PMID 27242785, 2016). "Mice depleted of CD4+ T-cells prior to secondary challenge cleared Pneumocystis infection within 48 h identical to immunocompetent mice during a secondary memory recall response." (PMID 27242785, 2016). "The host immune memory response during Pneumocystis infection involves a complex interaction between CD4+ T-cells, CD8+ T-cells, alveolar macrophages, and soluble factors that together facilitate clearance of the infection." (PMID 27242785, 2016). "Although CD4+ T cells are required for effective host defense against Pneumocystis infection, these cells also contribute to immune-mediated lung injury during Pcp." (PMID 21904545, 2011). "Animal models of SCID, Rag1−/−, Rag2−/− or, CD4+-T-cell-depleted mice directly demonstrate the role of CD4+ T cells in resistance to Pneumocystis infection." (PMID 21904545, 2011). "Although many studies have been dedicated to examining the role of CD4 cells in controlling Pneumocystis infection, it remains unclear which subset of T cells is necessary for this control." (PMID 38317180, 2024). "Clearance of Pneumocystis infection in mouse and humans requires CD4+ T cell immunity." (PMID 38446446, 2024). "CD4+ T cells have been believed to play an essential role in clearing Pneumocystis, as demonstrated by HIV-induced immunosuppressive patients with decreased CD4+ T cells susceptible to Pneumocystis infection." (PMID 37359523, 2023). "In conclusion, our findings suggest that B cells can secrete exosomes abundant in immune active protein contents, and these vesicles could modulate other immune cells such as CD4+ T cells in response to Pneumocystis infection." (PMID 35465354, 2022). "Vital roles of CD4+ T cells and macrophages in host defense against Pneumocystis have been well documented, considering that depletion of both cell populations results in the inability to control Pneumocystis infection." (PMID 35465354, 2022). "In addition, several studies have shown that proper CD4+ T-cell signaling is necessary for control of Pneumocystis infection." (PMID 33669726, 2021). "In addition, Pneumocystis infection induced the proliferation of clonal CD4+ T cells, and the expansion degree of clonal CD4+ T cells was greater than that of CD8+ T cells." (PMID 33959105, 2021). "Use of infliximab in an HIV-positive patient was associated with the occurrence of OI of P. jiroveci infection even with higher CD4+ count (above 240) than the suspicious level of Pneumocystis infection occurrence in HIV patients, which was thought due to TNF-α use with HIV infection." (PMID 33209528, 2020). "Nowadays, accumulating evidence indicates that B cells might play a vital role of promoting the proliferation and activation of CD4+ T cells during Pneumocystis infection." (PMID 31582901, 2019). "While the role of CD4 cells in controlling Pneumocystis infection is well documented, it remains unclear which T helper cell subset is absolutely necessary for this control." (PMID 29470553, 2018). "Additionally, CD4+ T-cells from Pneumocystis-infected mice are able to mediate clearance of Pneumocystis infection upon adoptive transfer into Rag1(−/−) mice." (PMID 27242785, 2016). "In addition, the transcriptomes of CD4+ T cells were altered during Pneumocystis infection." (PMID 38317180, 2024). "However, Dectin-2 seems not to play an essential role in controlling Pneumocystis infection in immunocompromised mice, as evidenced by Dectin-2–deficient, CD4-depleted mice having a similar outcome as wild-type control mice." (PMID 29470553, 2018). "Of these, naive CD4+ and CD8+ T cells showed a gradually decreasing trend, while effector CD4+ T cells significantly increased during the process of Pneumocystis infection." (PMID 38317180, 2024).
Pneumocystis infection (continued). "Among these, naive CD4+ and CD8+ T cells gradually decreased, while effector CD4+ T cells significantly increased during Pneumocystis infection." (PMID 33959105, 2021). "If immune-reconstituted mice are depleted of CD8+ T cells, they are able to clear the Pneumocystis infection but develop severe inflammatory disease, with increased IFN-γ production and a prolonged CD4+ T cell response compared to fully reconstituted mice." (PMID 21904545, 2011). "Co-trimoxazole prophylaxis against pneumocystis infection is effective and widely available and prescribed to patients newly diagnosed with HIV presenting with a CD4 count of <200 cells/μL." (PMID 21528786, 2011). "Furthermore, depletion of CD4+ T cells in mice leads to the development of PCP, and in SCID mice, which lack a T and B lymphocyte response, spontaneous Pneumocystis infection is observed within three weeks." (PMID 33669726, 2021). "Furthermore, adoptive transfer of memory CD4+ T cells is required for NK cell upregulation of activation maker NK group 2D, and production of IFN-γ, granzyme B, and perforin during Pneumocystis infection in mice." (PMID 33669726, 2021). "All MIIG positive and negative offspring were resistant to Pneumocystis infection when CD4-depleted and infected, demonstrating that macrophage IFNγR signaling was not required for the observed FVB resistance to Pneumocystis." (PMID 30283457, 2018). "In this study, we evaluated the cellular immune memory recall response to murine Pneumocystis infection in the absence of CD4+ T-cells." (PMID 27242785, 2016). "In addition, a role for CD8+ T cell subsets in controlling Pneumocystis infection in the absence of CD4+ T cells has also been reported." (PMID 30283457, 2018). "Furthermore, CD4/CD8 double-depleted FVB mice remained resistant to Pneumocystis infection, demonstrating that CD8+ T cells are not required for the CD4+ T cell independent resistance of FVB mice." (PMID 30283457, 2018).